INS (insulin)
Diseases named in the same sentence as INS in open-access papers (continued):
Sharing a sentence is not in itself a finding about the gene and the disease.
tumor (continued). "The disconnect between metabolic dysfunction and tumor suppression in KD-fed mice calls for further study of tissue-specific insulin signaling." (PMID 41398969, 2025). "Increased expression and activation of this pathway was discovered in insulinoma tumors and appears to be involved in upregulating tumor growth and insulin secretion." (PMID 40648766, 2025). "Metformin suppresses tumorigenesis by reducing serum glucose and insulin levels, acting on tumor cells and exerting its antitumor biological effects through AMPK-dependent and/or AMPK-independent signaling pathways." (PMID 40885703, 2025). "Inhibitors of SLC13A5 can reduce fat accumulation, enhance insulin sensitivity, and inhibit tumor cell proliferation." (PMID 41425581, 2025). "Metabolic dysregulation, such as insulin resistance or altered lipid metabolism, can affect the tumor microenvironment, influencing tumor growth and invasiveness." (PMID 40559215, 2025). "In particular, elevated insulin levels can accelerate tumor growth via the insulin-like growth factor (IGF) axis." (PMID 39395115, 2025). "These include hormonal dysregulation, chronic inflammation, altered adipokine signaling, insulin resistance, and activation of oncogenic intracellular pathways that collectively promote tumor progression, metastasis, and therapy resistance." (PMID 40869064, 2025). "Low-grade inflammation and gut microbial changes further enhance PI3K/AKT/mTOR and Wnt/β-catenin signaling, creating a tumor-promoting environment in insulin-resistant states." (PMID 41374004, 2025). "PC cells secrete tumor-inducing factors, such as adrenomedullin, leading to an increase in insulin resistance and beta cell dysfunction in PCDM." (PMID 40487412, 2025). "The excessive accumulation of reducing equivalents, such as NADH and NADPH, disrupts cellular redox balance, altering insulin secretion, vascular function, and tumor progression." (PMID 40076537, 2025). "Elevated insulin levels can enhance tumor growth through the insulin-like growth factor 1 (IGF-1) pathway, a signaling cascade known to promote cellular proliferation and inhibit apoptosis (programmed cell death)." (PMID 39518104, 2024). "Both mechanisms are mediated by a reduction of systemic insulin signalling induced by tumour-secreted insulin-like-peptide antagonist ImpL2 (Imaginal morphogenesis protein-Late 2)." (PMID 38429578, 2024). "Mice were assessed at 30 weeks of age (pre-tumour) for body composition, glucose tolerance, fed and fasted insulin levels, and HOMA-IR; however, the only phenotype observed was a 2.8-fold increase in fed insulin levels in A1KO mice vs. WT mice (p < 0.05)." (PMID 39538356, 2024). "Chronically elevated levels of glucose in blood can activate the insulin pathway and facilitate tumor progression, the repair of tumor cells after radiation therapy, or treatment resistance." (PMID 39180334, 2024). "In insulin-resistant states, T cell function is suppressed, leading to a reduced ability to recognize and eliminate tumor cells." (PMID 38449844, 2024). "Remarkably, these tumor cells mimic adipocytes by sending the Upd2/leptin signal to regulate insulin release, thereby controlling tumor growth." (PMID 39642218, 2024). "It has been well established that patients undergoing corticosteroid administration show increased levels of glycemia, lactate and insulin, with an unfavorable effect on tumor progression." (PMID 40041752, 2024). "We also showed that cyclin-E1-overexpressing tumours are enriched for genes involved in insulin signalling and release." (PMID 38612869, 2024). "Many cancer patients receive corticosteroids as prophylactic treatment against CRT side effects, but steroids can increase glucose and insulin levels, triggering growth signals in residual tumor cells as a collateral effect." (PMID 39195514, 2024). "Instead, it indicates a significant alteration in tumor insulin signaling in response to normal physiological fluctuations in insulin concentration." (PMID 38595915, 2024).
tumor (continued). "Neuroendocrine cells produce functional hormones like serotonin, insulin, glucagon, and gastrin, depending on the specific subtype of the tumor." (PMID 39211694, 2024). "At the same time, the observed effects on cell proliferation, differentiation, angiogenesis, and drug resistance shed light on the complex interplay between insulin signaling and tumor biology." (PMID 38331804, 2024). "Recently, it has been shown that senescence acts as a tumor promoter and stimulates skin cancer by upregulating p38MAPK and MAPK/ERK signaling, upon which the high insulin levels associated with IR also act." (PMID 39457728, 2024). "Insulin can directly promote tumor development by stimulating cell proliferation and activating the IGF1 system, which controls cell differentiation, proliferation, and apoptosis." (PMID 39064705, 2024). "Previous studies have demonstrated that IGFBP3 negatively modulate the insulin secretion and insulin signaling pathway, exerting inhibitory effects on tumor cell proliferation and progression." (PMID 38952983, 2024). "In scrib−/− mutant cells, hyperinsulinemia (high levels of circulating insulin) systematically abrogates tumour-suppressive cell competition by boosting InR-mTOR-mediated protein synthesis in premalignant cells." (PMID 39682725, 2024). "In the same mouse model, a later study found that decreasing circulating insulin levels in these mice decreases tumor growth." (PMID 39642218, 2024). "Adiponectin shows anti-tumor activity because of its anti-inflammatory and anti-proliferative effects and its antagonistic effect on insulin." (PMID 38261736, 2024). "The contents of AT-exos have been shown to exert complex regulatory effects on local inflammation, tumor dynamics, and insulin resistance." (PMID 39220365, 2024). "Mechanistically, mitochondrial defects result from reduced muscle insulin signalling, downstream of tumour-secreted insulin growth factor binding protein (IGFBP) homologue ImpL2." (PMID 38429578, 2024). "Insulin was suggested to promote tumor progression through INSR‐A with activation of AKT/mTOR signaling." (PMID 38952575, 2024). "It acts as a transcription factor to regulate insulin, controls genes that regulate cell growth and survival, and acts as a tumor suppressor." (PMID 38540215, 2024). "SSAs bind specifically to somatostatin receptors (SSTRs) to prevent tumor-activated endocrine regulators that result in tumor growth, such as insulin, gut hormones, TSH, and growth hormones (GHs)." (PMID 39456853, 2024). "Both cachectic adult tumour models exhibit hyperglycaemia (increased trehalose, a kind of blood sugar) due to the systemic reduction in insulin signalling by tumour-derived ImpL2." (PMID 39682725, 2024). "First, tumour-secreted ImpL2 systemically decreases insulin signalling, which results in an increase in FOXO nuclear localisation in the muscle." (PMID 38429578, 2024). "The human granulosa-like tumor cell line KGN was incubated with insulin to assess the effects of lncRNA SNHG12 on GC proliferation and apoptosis." (PMID 38566229, 2024). "Dilp2 then activates the insulin signaling in the tumor, thereby fostering sexual-dimorphic tumor growth." (PMID 39642218, 2024). "TACE was employed to reduce tumor burden by delivering chemotherapeutic agents directly to the tumor vasculature while inducing ischemia, potentially reducing insulin secretion." (PMID 39677258, 2024). "In the RasV12scrib−/− and RasV12dlgRNAi tumour models in the larval developing eye, the tumour-secreted ImpL2 systemically decreases insulin signalling, altering the activity of the transcription factor FOXO in the muscle." (PMID 39682725, 2024). "It manifests with various signs and symptoms, depending on tumor size, insulin levels, and disease duration." (PMID 39330031, 2024).
tumor (continued). "KMT is a potential biomarker-driven metabolic therapy to lower glycolytic SLP, insulin, and oncogenic signaling below baseline, while also stabilizing the tumor microenvironment, contingent upon biological compliance and impacts from other therapies." (PMID 39639257, 2024). "Functional tumours are uncommon and produce hormones and peptides including insulin, gastrin, vasoactive intestinal peptide (VIP), glucagon, somatostatin, and serotonin." (PMID 39246612, 2024). "The insulin signaling pathway plays a crucial modulatory role in tumorigenesis and tumor advancement." (PMID 38952983, 2024). "Conversely, treatment approaches that reduce serum insulin levels (e.g. ketogenic diet, sodium glucose co-transport 2 inhibitor (SGLT2i)) enhance the anti-tumor effects of PI3K inhibitors." (PMID 39437820, 2024). "The confirmation of Whipple's triad (neuroglycopenic symptoms, confirmed low plasma glucose levels during symptoms, and prompt relief of symptoms following the consumption of glucose) solidified the clinical suspicion of an insulin-secreting tumor." (PMID 39677258, 2024). "We have also shown the CCNE1-overexpressing tumours are enriched in genes involved in insulin signalling and release." (PMID 38612869, 2024). "The specificity of this analysis was supported by the downregulation of the acinar and insular cell markers AMY2B and INS, while the expression of the tumor marker KRT19 was increased (Fig. EV3A)." (PMID 38413734, 2024). "This is interesting as in another study, tumor-derived exosomal miRNA let-7a is shown to affect insulin-Akt-mTOR pathway increasing OXPHOS metabolism and M2 polarization under hypoxia conditions." (PMID 39260692, 2024). "Persistent high levels of insulin can promote generation of an inflammation environment, which plays a key role in tumor initiation and progression." (PMID 39290325, 2024). "Insulin is a potential oncogenic factor involved in stimulation of cell proliferation, including malignant tumor cells." (PMID 39497166, 2024). "This is due to the fact that high levels of insulin in the bloodstream increase mitosis and tumour cell growth and proliferation." (PMID 39588310, 2024). "Aspirin, DPP-4 inhibitors, and metformin are associated with improved outcomes, while insulin use and pre-TKI statin use are linked to an increased risk of mortality and tumor recurrence in statin users." (PMID 38254739, 2024). "The insulin and insulin-like growth factor axis promotes tumor progression through direct proproliferative effects and indirectly through alterations in glucose metabolism." (PMID 38395868, 2024). "Metformin can also target ATP production, impairing respiratory chain function and inhibiting the growth of insulin-dependent tumor cells, though the mechanisms of metformin’s action and its clinical dosing are still under investigation." (PMID 39763653, 2024). "It has been observed that high dietary sugar (HDS) increases tumor cell insulin sensitivity and sugar influx, thereby promoting tumor progression through upregulation of wingless/Wnt signaling." (PMID 39261338, 2024). "The insulin/IGF1 growth axis has been implicated as a poor prognostic marker, not as an oncogenic pathway, but as a proliferative additive to the unregulated tumor cell signal." (PMID 39195514, 2024). "For instance, recent studies have described a similar mechanism for mTORC1 regulation by folliculin, a regulator of the RAGC GTP-binding protein that converges with insulin signaling and mTORC1 regulation in tumor growth." (PMID 38396745, 2024). "The platinum, paclitaxel, and cyclophosphamide used during the NAT in this study kill tumor cells and damage pancreatic islet β-cells, decreasing insulin secretion, abnormal glucose tolerance, and elevated blood glucose." (PMID 38725003, 2024). "Correspondingly, enhanced oxidative stress and glycolysis, insulin, progesterone, and corticosterone activity all enhanced the tumor immunity in the HPV− group." (PMID 39346086, 2024).
tumor (continued). "Healthy Brown Norway (BN), mild diabetic Zucker diabetic fatty (ZDF), and Rat1-myr-p110α/HBRX3077 tumor–bearing nude rats treated with alpelisib were analyzed for glucose and insulin control with metformin and dapagliflozin (SGLT2i) and alpelisib efficacy." (PMID 39177931, 2024). "In MCF-7 tumor cell lines, estradiol facilitates insulin signaling through an increased expression of insulin receptor substrate-1 (IRS-1)." (PMID 39329990, 2024). "High expression of insulin/IGF1R positively correlated with a high level of infiltration of macrophages in the tumor, as well as advanced tumor stages." (PMID 37237509, 2023). "Elevated insulin levels indirectly or directly promote tumor cell proliferation and reduce apoptosis through the production of other hormones, such as insulin-like growth factor (IGF-1)." (PMID 37940857, 2023). "Pegvisomant has a neutral effect on tumour size, and beneficial effects on blood sugar metabolism (reduction in fasting insulin, fasting blood sugar, HbA1c and increased insulin sensitivity)." (PMID 37507554, 2023). "After the occurrence of metabolic disorders, insulin activates the paracrine connection between tumor cells on the CXCL1/CXCR12 axis and CAFs, triggering the movement phenotype of tumor cells." (PMID 37978384, 2023). "Insulin administration significantly increased 18F-FDG uptake in tumor tissue, liver, and heart in diabetic animals but did not have a significant impact on 18F-FDG uptake in blood, skeletal muscle, kidneys, and brain." (PMID 37884546, 2023). "In this study, we show that insulin signalling (regulated by tumour‐derived ImpL2) directly affects muscle translation rates and atrophy." (PMID 38014610, 2023). "Even though insulin can induce direct tumor growth, its mitogenic and antiapoptotic effects also result in tumor cell growth." (PMID 38068717, 2023). "miRNAs influence the expression of tumor suppressor genes, and studies have shown that miRNAs related to the patient’s immune microenvironment and insulin status can predict the future development of EC." (PMID 37152960, 2023). "SHIP2 is a phosphatase with oncogenic properties, associated with activation of ERK, AKT, insulin and JAK-STAT signaling, but also has some tumor suppressor functions." (PMID 37686522, 2023). "Together with an additional defining element of PDAC, i.e., increased insulin levels, this activation allows augmented uptake of glucose by the tumor cells through GLUT4 membrane translocation, thus promoting growth and chemoresistance of PDAC." (PMID 38078007, 2023). "It is accurate to say that increased levels of insulin, IGF-1, and IGF-2 in the blood circulation are directly linked to the onset and spread of the majority of tumours." (PMID 36890832, 2023). "These potential mechanisms can lead to increased insulin levels in the pancreatic microenvironment and further contribute to tumor development." (PMID 36672448, 2023). "BAT removal improved fast blood glucose, insulin, c-peptide, tumor cell proliferation, and tumor hypoxia, favoring tumor growth." (PMID 37993438, 2023). "Tumor cells as well as cardiac cells can act as endocrine organs by releasing or affecting the release of hormonal signals such as insulin, IGF‐1, growth hormone, as well as inflammatory cytokines." (PMID 37654192, 2023). "Additional investigative efforts are warranted to examine the role of insulin signaling and resistance in tumor-specific immunity." (PMID 36992811, 2023). "Among various factors favoring tumor progression and metastasis, dysregulation of the insulin/IGF system (IIGF) has attracted much attention and is now considered a well-established contributor and possible target." (PMID 36672737, 2023). "In the noncachexia stage, tumor cell growth is in its initial phase, and acetate is utilized by tumor tissues to provide energy, while glucose is trapped at a high level due to chronic inflammation and insulin resistance." (PMID 37705348, 2023).
tumor (continued). "Considering that loss of PTEN results in lower insulin resistance and lipogenesis, which is responsible for tumor microenvironment establishment, NEDD4 reprograms metabolic status and tumor progression through PTEN ubiquitination." (PMID 37176148, 2023). "Insulin levels increase insulin-like growth factor-1 (IGF-1) activity, important in tumour initiation and progression, and is associated with increased oestrogen bioavailability, which promotes breast carcinogenesis." (PMID 36737658, 2023). "Knowing that insulin stimulates cellular proliferation and signaling pathways, decreasing insulin levels will indirectly suppress the tumor-stimulating pathways." (PMID 36661704, 2023). "A significant increase in insulin level was observed, especially in the gastroduodenal and proximal splenic arteries, indicating localization of an insulin-secreting tumor in the pancreatic body and tail." (PMID 37563593, 2023). "Third, high BMI increases the circulating levels of insulin and insulin‐like growth factor 1, promoting cell proliferation, tumor initiation, tumor growth, tissue invasion, and metastatic progression." (PMID 36806718, 2023). "Adiponectin acts as an insulin-sensitizing, anti-inflammatory, and anti-tumor agent, the latter by inhibiting cell proliferation and angiogenesis and increasing apoptosis." (PMID 38004062, 2023). "SIRT1 is an NAD+-dependent protein deacetylase that has been shown to play a significant role in many biological pathways, such as insulin secretion, tumor formation, lipid metabolism, and neurodegeneration." (PMID 37711385, 2023). "A fasting mimicking diet (FMD) targets insulin signaling pathway downregulation to hamper tumor growth." (PMID 38136416, 2023). "Co‐expression of InRCA and madRNAi gave a similar rescue as either InRCA (InRCA;mCherryRNAi) or madRNAi(madRNAi;LacZRNAi) alone, suggesting that TGF‐β signalling likely acts downstream of insulin signalling in the fat body of tumour‐bearing animals." (PMID 38014610, 2023). "Transfer of faeces from obese mice treated with metformin into untreated mice inhibited tumour growth independently of changes in body mass, blood glucose or serum insulin." (PMID 36823364, 2023). "The insulin-secreting tumor was 10-mm in diameter and consisted microscopically of atypical cells positive for chromogranin A, synaptophysin and insulin but negative for glucagon and somatostatin." (PMID 37563593, 2023). "To test this, we activated insulin signalling in the muscle of tumour bearing animals (QRasV12, scribRNAi) by overexpressing Akt with the muscle‐specific driver MHC‐GAL4." (PMID 38014610, 2023). "This study is the first to discover the SGLT2 inhibitor can effectively reduce 18F-FDG uptake in skeletal muscle and significantly increase the tumor-to-skeletal muscle ratio in diabetic mice compared with insulin." (PMID 37884546, 2023). "Although the gene was first identified as a tumor suppressor, it has recently been shown to be important with its antagonistic function in the insulin signaling cascade and is involved in glucose metabolism." (PMID 36997916, 2023). "The KEGG pathway and GO biological process analyses showed enrichment of vesicle-mediated transport, vital in tumor microenvironment remodeling and transport of secretory insulin or other circulating mediators in diabetes." (PMID 38114687, 2023). "Meanwhile, glycolysis and anabolism elicited by insulin affect tumor cells displaying a hybrid metabolic situation." (PMID 36836124, 2023). "She then underwent spleen-preserving distal pancreatectomy; a 10-mm tumor positive for chromogranin A, synaptophysin and insulin was identified." (PMID 37563593, 2023). "Insulin, in turn, is an anabolic hormone that accelerates glucose uptake and stimulates mitosis, which can promote tumor cell proliferation." (PMID 36900268, 2023).